IGF1 (insulin like growth factor 1)
Diseases named in the same sentence as IGF1 in open-access papers (continued):
Sharing a sentence is not in itself a finding about the gene and the disease.
myeloma (continued). "Myeloma cells secrete angiogenic factors such as VEGF, hepatocyte growth factor (HGF), fibroblast growth factor-2 (FGF-2), and insulin like growth factor-1 (IGF-1), thereby enhancing cell proliferation and survival." (PMID 41471085, 2025). "Apart from IL-6, BMSCs additionally produce VEGF, IGF1 or SDF-1, soluble factors that have been shown to directly or indirectly affect myeloma growth, migration and invasion." (PMID 37744361, 2023). "NF-kB activity in myeloma cells is important for maintaining the interaction with BM stromal cells, because this factor regulates the expression of IL-6, VEGF, and IGF-1, which provides the survival, development, and chemoresistance of myeloma cells around BM." (PMID 36678608, 2023). "IGF-1, which are secreted from BMSC and autocrined by MM cells, binds with IGF-1R, contributing to the proliferation of myeloma cells and CAM-DR." (PMID 33435539, 2021). "Targeting the GLUT and MCT transporters, IGF-1, FAS, ETC and OXPHOS need to be further explored as potential anti-myeloma therapeutic strategies." (PMID 34768861, 2021). "The adhesion of myeloma cells to BMSC induces the secretion of several cytokines and growth factors, such as interleukin (IL)-6, and insulin-like growth factor-1 (IGF-1)." (PMID 33435539, 2021). "HIF-1a is downstream of the PI3K/AKT/mammalian target of rapamycin (mTOR) pathway and is associated with the progression of myeloma cells through the transcription of several important genes concerning myeloma pathogenesis, such as VEGF and IGF-1." (PMID 33435539, 2021). "Therefore, given our demonstration that IGF-1 confers resistance to combined trametinib and dexamethasone, it was possible that the synergistic effects observed in myeloma cells cultured in vitro may be blunted in vivo due to signalling cues from the supporting stroma." (PMID 32228485, 2020). "Targets such as the GLUT and MCT transporters, IGF-1, FAS, and metabolites of the ETC and OXPHOS warrant additional exploration as possible novel anti-myeloma strategies, but care must be taken to minimize adverse effects when targeting ubiquitous pathways." (PMID 31020046, 2019). "Bacterially produced IGF-1 was co-immunoprecipitated (co-IPed) with recombinant IGFBPL1, which was purified from a mouse myeloma cell line." (PMID 29391597, 2018). "PIs suppress the production of cytokines including interleukin-6 (IL-6), insulin-like growth factor 1 (IGF-1), and tumor necrosis factor α (TNFα), which can affect MSC and myeloma cell interactions." (PMID 29765356, 2018). "An important role of the IGF-1/IGF-1R for proliferation and survival of malignant cells was described in mulitple myeloma, mantle cell lymphoma as well as Hodgkin’s lymphoma." (PMID 28456850, 2017). "In this study we identified IGFBP7, a secreted factor with BMP antagonistic activity, and binding sites for IGF-1, insulin, VEGFA and activin A as a potential novel player in the pathogenesis of MM, including myeloma bone disease." (PMID 25887188, 2015). "IGF1 signaling through PI3-K/Akt and β1 integrin similarly promotes adhesion and migration in multiple myeloma cells." (PMID 24708576, 2014). "For example, IL-1β, IL-6, IL-10, IFN-α, IGF-1 and TGF-γ promote proliferation of multiple myeloma cells, whereas IFN-β1 and APO-1/FAS inhibit the growth of multiple myeloma cells." (PMID 22792345, 2012). "Given the importance of IGF-1 in myeloma biology, we specifically examined the effect of MK-2206 on inhibiting PI3K/Akt/mTOR pathway in the presence of IGF." (PMID 23185517, 2012). "Western-blots detected increased p-STAT3 in these CKS1B-silenced myeloma cells compared with untreated, SCR- or CKS1B-shRNA-transfected controls, confirming activation of STAT3 in IGF-1-treated cells." (PMID 20930946, 2010). "IGF-1 is an other essential growth factor for myeloma cells and inhibition of the IGF-1-pathway reduces myeloma cell growth both in vitro and in vivo." (PMID 20465808, 2010).
myeloma (continued). "Insulin-like growth factor-1 (IGF-1) has been described as an important factor in proliferation, cell survival and migration of multiple myeloma (MM) cells." (PMID 14997210, 2004). "However, the inhibitory effect was decreased with the addition of IL-6 and IGF-1, two primary compounds for inducing the PI3K signaling pathway in myeloma cells." (PMID 40922746, 2025). "The bone marrow microenvironment plays a crucial role in the progression of multiple myeloma by secreting a range of cytokines and growth factors (e.g., IL-6, VEGF, TGF-β, IGF-1, CXCL12) that support the survival, proliferation, and resistance to apoptosis of myeloma cells." (PMID 38831183, 2024). "For example, in multiple myeloma cells, IL-6, one of the key inflammatory factors, and insulin-like growth factor 1 (IGF1) increased telomerase activity without changing the level of TERT expression." (PMID 37189709, 2023). "In turn, endothelial cells will produce IGF1 and IL6 to promote myeloma cell growth." (PMID 33634031, 2020). "To clarify the role of PI3K/AKT/mTOR signaling in the regulation of multiple myeloma cell proliferation and apoptosis by CIP2A, we evaluated the effect of IGF-1 which could activate PI3K on RPMI-8226 and NCI-H929 cells." (PMID 27144172, 2016). "Future studies investigating connections between the insulin/IGF-1/AS160_v2/GLUT4 axis and FDG-PET positivity in myeloma patients are warranted and could provide rationale for therapeutically targeting this pathway in MM patients with advanced disease." (PMID 24280290, 2013). "In a non-tumor model, ROSI has been reported to inhibit the activities of those two factors; in myeloma cell line, ROSI inhibits insulin-like growth factor 1 (IGF-1) or HIF-1α, which could boost VEGF’s pro-angiogenesis effects, via PI3K/AKT and ERK signaling in a PPAR-γ-dependent fashion." (PMID 34631571, 2021). "IGF-1 is an endocrine factor produced and secreted by bone marrow stromal cells (BMSC), bone endothelial cells, and osteoblasts that promotes the homing, growth, and survival of myeloma cells in the bone marrow environment, both dependent and independent of IL-6." (PMID 33531904, 2021). "BZT also decreases adhesion of myeloma plasma cells to stromal cells and disrupts secretion of specific cytokines in the bone marrow microenvironment such as vascular endothelial growth factor (VEGF), insulin-like growth factor 1 (IGF-1), interleukin-6 (IL-6), and tumor necrosis factor-α (TNF-α)." (PMID 31979371, 2020). "Importantly, activated platelets secrete many cytokines that are required for growth of myeloma cells including IL-6, VEGF, SDF-1α, and IGF-1, suggesting that platelets may affect the microenvironments of MM." (PMID 27852046, 2017). "Several key questions about this activation mechanism remain unanswered, including how clustering of Sdc1 activates IGF1-R independent of IGF1 ligand, how SSTNIGF1R blocks IGF1 stimulation of IGF-1R in myeloma and whether SSTNIGF1R blocks IGF1-induced IGF-1R activation in tumors other than myeloma." (PMID 34778093, 2021). "Notably, addition of insulin-like growth factor 1 and interleukin-6, two important triggers for PI3K activation in MM cells, partly blocked BENC-511-induced MM cell death, which further demonstrated that PI3K signaling pathway was critical for the anti-myeloma activity of BENC-511." (PMID 24428908, 2014). "However, in contrast to myeloma cells, incubation of undifferentiated C2C12 cells with different concentrations of IGF-1 did not result in activation of PKD2 (data not shown)." (PMID 21298052, 2011). "Also unique to the myeloma cells compared to carcinoma or endothelial cells is that IGF-1R in the pre-assembled Sdc1-coupled ternary receptor complex is constitutively active; it is not dependent on cell adhesion or IGF-1, although exogenous IGF1 stimulates increased levels of IGF-1R activation." (PMID 34778093, 2021).
myocardial infarction (98 papers, 2009 to 2026). Gross necrosis of the myocardium, as a result of interruption of the blood supply to the area, as in coronary thrombosis. "When applying FDR correction, additional cardiovascular phenotypes showed significant associations in females, such as a paternal history of heart attack, systolic blood pressure, insulin-like growth factor 1 (IGF-1), and haemoglobin concentration." (PMID 36512526, 2022). "In patients with acute myocardial infarction, noticeably reduced IGF-1 levels are linked with a poor outcome." (PMID 33905470, 2020). "The present results demonstrate that intra-myocardial injection of HGF and IGF-1 in a rat model of healed myocardial infarction caused a significant decline in arrhythmias of conscious freely moving animals subjected to stressful conditions." (PMID 21445273, 2011). "Decreased expression of IGF-1 during myocardial infarction was linked with a worse prognosis." (PMID 39728482, 2024). "Low circulating IGF-1 levels may also predict for increased risk of heart disease and myocardial infarction." (PMID 33816541, 2021). "Local IGF-1 signaling in heart has anti-apoptotic and regenerative effects and is associated with improvements in cell growth, contractility, cardiac output, stroke volume, ejection fraction, functional recovery following myocardial infarction and insulin sensitivity." (PMID 29708498, 2018). "We took an approach to autocrine insulin-like growth factor 1 (IGF1) protein in situ by transfecting IGF1 modified mRNA into TECPs just prior to cardiac transplantation in a rat myocardial infarction model." (PMID 41560804, 2026). "The TECPs secreting IGF1 also aided in the tissue integrity of the heart muscle morphology and the cardiac function repair after myocardial infarction." (PMID 41560804, 2026). "IGF-1 has been proven to boost heart function after myocardial infarction and to induce cardiomyocyte growth." (PMID 40407974, 2025). "In patients recovering from myocardial infarction, low-intensity aerobic training predominantly elevates IGF-1 and NRG1 levels while mitigating exercise-induced cardiovascular risks." (PMID 41000109, 2025). "In human studies, IGF-1 stimulates contractility and tissue remodeling, improving heart function after myocardial infarction." (PMID 41514592, 2025). "Rat ADP MSCs expressing IGF1 secreted higher levels of IGF1 and improved the prognosis of myocardial infarction." (PMID 38392291, 2024). "IGF-1 stimulates contractility and tissue remodeling in humans to improve heart function after myocardial infarction." (PMID 36843588, 2023). "Free IGF-1 levels have been shown to be higher in patients with myocardial infarction compared to controls." (PMID 37372424, 2023). "Among patients who suffered acute myocardial infarction, plasma levels of IGF-1 and IGFBP-2 were lower and higher, respectively, as compared to healthy controls (both p < 0.05)." (PMID 36970368, 2023). "High IGF-1 group patients were found to have a higher ejection fraction (EF), a lower rate of acute myocardial infarction (AMI) and a higher rate of multi-vessel lesion as compared to those in the low IGF-1 group." (PMID 36970368, 2023). "Almost all studies of cardioprotection with insulin and IGF1 have used models of myocardial infarction with cardiomyocytes or the heart subjected to hypoxia/ischaemia followed by reoxygenation/reperfusion." (PMID 35766350, 2022). "In an animal model of acute myocardial infarction, the transplantation of adipose-derived MSCs (ADSCs) that overexpressed both IGF-1 and HGF to the injured area promoted neovascularization and suppressed inflammation." (PMID 36233084, 2022). "In lined with our findings, it was previously reported that IGF-1 over-expressed MSCs exhibited more resistant to apoptosis and higher cell viability under hypoxia in myocardial infarction model." (PMID 35033199, 2022).
myocardial infarction (continued). "Insulin and IGF1 can be cardioprotective: insulin/IGF1 reduce infarct size in ex vivo models of myocardial infarction, and cardiomyocyte-specific expression of IGF1 in mice protects against myocardial infarction in vivo." (PMID 35766350, 2022). "In the isoproterenol-induced myocardial infarction model, IGF-1 promotes angiogenesis through inducing IL-8 expression." (PMID 36091401, 2022). "IGF-1 treatment in rats with myocardial infarction can promote VEGF expression and improve the degree of myocardial ischemia." (PMID 36091401, 2022). "For other disease, such as myocardial infarction, bone marrow-derived mononuclear cells used for treatment release IGF-1, which blocks cardiomyocyte apoptosis." (PMID 36294819, 2022). "IGF-1 is a known anti-apoptotic factor, and it has been demonstrated that sustained release of IGF-1 from ADSCs protected cardiomyocytes from apoptosis following myocardial infarction." (PMID 34638927, 2021). "Recent studies have shown that short-term IGF-1 treatment (1 μg/g/day) using an osmotic minipump for 3 days after acute myocardial infarction improves cardiac function by modulating the acute inflammatory phase but does not alleviate fibrosis." (PMID 34244467, 2021). "For example, low-dose (600 pg) intracoronary IGF-1 administered following reperfusion in a porcine model of myocardial infarction was shown to have acute pro-survival effects on the myocardium." (PMID 34244467, 2021). "Insulin-like growth factor-1 (IGF-1) has demonstrated beneficial effects after myocardial infarction (MI)." (PMID 32346015, 2020). "Downregulation of IGF-1 during I/R through microRNA-320 and microRNA-489 aggravated the extent of myocardial infarction, ventricular remodeling, and apoptotic cell death, proposing an important IGF-1 mediated endogenous protection against ischemic cell death." (PMID 33317180, 2020). "In our recently published study, we reported that in rat with acute myocardial infarction, transplantation of bone marrow mesenchymal stem cell overexpression insulin-like growth factor-1 greatly reduced infarct volume and myocardial fibrosis." (PMID 32454934, 2020). "After an acute myocardial infarction, IGFBP-3 and IGF-1 levels significantly increased, which was associated with improved outcomes and echocardiographic parameters (LV dimensions, mass and ejection fraction)." (PMID 32831121, 2020). "The hybrid hydrogel system can co-deliver 6-Bromoindirubin-3-oxime (BIO) and insulin-like growth factor 1 (IGF-1) to areas of myocardial infarction and thus improve cardiac function by promoting the proliferation of cardiomyocytes and revascularization." (PMID 32676024, 2020). "Transplantation of BMSCs in acute myocardial infarction rats was used to explore the effect of BMSCs-IGF-1 therapy." (PMID 31918758, 2020). "Recently it was demonstrated that subcutaneous IGF-1 supplementation for 3 days improved cardiac function after myocardial infarction." (PMID 33317180, 2020). "Intravenous injection of IGF-1 30 min before left anterior descending artery ligation ameliorated myocardial infarct size and apoptosis." (PMID 33317180, 2020). "This is further affirmed by the findings that genetic depletion of mouse mast cell protease 4—presumably responsible for endogenous IGF-1 degradation—alleviated myocardial infarct size, post-ischemic cardiac dysfunction and remodeling." (PMID 33317180, 2020). "Short-term anti-inflammatory properties of IGF-1 seem to decrease infarct size and promote left ventricular remodeling after myocardial infarction." (PMID 33905470, 2020). "Transplantation of BMSCs-IGF-1 into myocardial infarction rats greatly reduced infarct volume than BMSCs-NC, with significantly greater expression of SFRP2 and β-catenin." (PMID 31918758, 2020). "Other mouse model research noted a cardiomodulating and cardioprotective influence of a synthetic analog of the MGE peptide, administered during myocardial infarction and affecting local production of mature IGF1." (PMID 32977489, 2020).
myocardial infarction (continued). "The influence of different IGF1 isoforms is also studied in different models of cardiac muscle repair (mostly myocardial infarction related)." (PMID 32977489, 2020). "During myocardial infarction, SH groups, IGF-1, insulin, hsCRP, and PSP were significantly different when compared to the control group." (PMID 31540292, 2019). "VEGF, bFGF, HGF and IGF‐1 contents in the CSps group were 3.06, 8.75, 1.61 and 2.54 times those in the Control group, respectively (P < 0.05) at 1 week after myocardial infarction." (PMID 29736937, 2018). "Intramyocardial administration of IGF-1 also decreases the infarct size and cardiac dysfunction following myocardial infarction in rats." (PMID 29547524, 2018). "Direct assessment of the content of growth factors showed that VEGF, bFGF, HGF and IGF‐1 in pericardial effusion from the CSps group were many fold higher than those from the Control group at both early and late time points after myocardial infarction." (PMID 29736937, 2018). "The aim of this study was to explore the cardioprotective and angiogenesis effects of HWJMSCs combined with insulin-like growth factor-1 (IGF-1) in the treatment of acute myocardial infarction." (PMID 29881402, 2018). "Here, we evaluated the combination of cell- and gene-based therapy using mesenchymal stem cells (MSC) genetically modified to overexpress IGF-1 or HGF to treat acute myocardial infarction (AMI) in a porcine model." (PMID 27423905, 2016). "Previous approaches utilizing gene- and cell-based methods to deliver IGF-1 after myocardial infarction through permanent occlusion of the left coronary artery demonstrated an amelioration of PIR." (PMID 23437254, 2013). "CSCs and the intramyocardial injection of HGF and IGF-1 resulted in the regeneration of the infarcted area and newly formed myocardial tissue at 20 days after the induction of myocardial infarction in rat hearts." (PMID 23407679, 2013). "Further, it has been reported that combined intra-myocardial application of VEGF-a and IGF-1 is closely related to a better myocardial function and a lower rate of heart failure after acute myocardial infarction in rats." (PMID 23437254, 2013). "In myocardial infarction, the upregulated miR-206 induces cell apoptosis via insulin-like growth factor 1 (Igf1)." (PMID 23823624, 2013). "In studies on rats, cell therapy with insulin-like growth factor 1 delivery by biotinylated nanofibers improved systolic function after experimental myocardial infarction." (PMID 23889805, 2013). "Adult female rats were examined during pregnancy, after myocardial infarction and ischemia-reperfusion injury with/out insulin like growth factor-1(IGF-1) and hepatocyte growth factor (HGF)." (PMID 22590612, 2012). "Administration of IGF-1 after myocardial infarction improves cardiac function through the increase of myocardial growth." (PMID 23508361, 2012). "In the myocardial infarction group there was a divergent reactivity, with marginal up-regulation of IGF-1 (P = 0.06), especially at the site of injury and significant (P<0.05) down-regulation of endogenous HGF." (PMID 22590612, 2012). "In conclusion, treatment with insulin-like growth factor-1 (IGF-1) in myocardial infarction significantly increased circulating angiogenic growth factors like IGF-1, VEGF and TGF beta thus, protecting against myocardial ischemia." (PMID 21651821, 2011). "Numerous studies have shown that IGF1 inhibits apoptosis, promotes cell proliferation, enhances neovascularization, protects the heart from oxidative stress injury, and aids in the recovery of cardiac function following myocardial infarction." (PMID 41560804, 2026). "Conversely, post-myocardial infarction exercise promotes angiogenesis via IGF-1/VEGF signaling." (PMID 41000109, 2025). "Furthermore, it was found that IGF-1 attenuates the pro-inflammatory phenotype of neutrophils in myocardial infarction." (PMID 39355348, 2024).